HHLA2 (HHLA2 member of B7 family)
Description:
Through interaction with TMIGD2, costimulates T-cells in the context of TCR-mediated activation. Enhances T-cell proliferation and cytokine production via an AKT-dependent signaling cascade.
Synonyms: B7H7; B7-H5; B7y; B7-H7
Tractability: Antibody: UniProt predicts a signal peptide or a membrane-spanning region.
Gene: Protein-coding gene on chromosome 3 (108,295,334 to 108,379,814, forward strand). Ensembl gene ENSG00000114455.
Subcellular location: Membrane
Gene Ontology:
Molecular function: protein binding; signaling receptor binding
Biological process: positive regulation of activated T cell proliferation; positive regulation of cytokine production; T cell costimulation; regulation of cytokine production; T cell receptor signaling pathway; regulation of leukocyte cell-cell adhesion; regulation of T cell activation
Cellular component: external side of plasma membrane; membrane
Genetic constraint (gnomAD): Loss-of-function variants: 40 observed, 39.36 expected, observed/expected ratio (o/e) 1.02, 90% interval 0.79 to 1.32. The upper end of that interval is the gene's LOEUF score, 1.32, which puts it in group 5 of 6, group 1 being the genes least tolerant of losing a copy. Missense variants: 413 observed, 462.29 expected, observed/expected ratio (o/e) 0.89, 90% interval 0.82 to 0.97. Synonymous variants: 151 observed, 165.67 expected, observed/expected ratio (o/e) 0.91, 90% interval 0.8 to 1.04.
Homologues: Orthologues: chimpanzee HHLA2 (98% identical), macaque HHLA2 (81% identical), pig HHLA2 (59% identical), tropical clawed frog hhla2 (25% identical). Paralogues in human: BTN3A3 (17% identical), BTN1A1 (16% identical), CD276 (16% identical), BTN3A1 (16% identical), BTNL9 (15% identical), VTCN1 (15% identical), BTN2A1 (15% identical), BTN2A2 (15% identical), BTNL8 (14% identical), BTN3A2 (14% identical), BTNL3 (14% identical), ICOSLG (14% identical), and 3 more.
Diseases named in the same sentence as HHLA2 in open-access papers:
HHLA2 is named in the same sentence as 83 diseases in open-access papers, as found by Europe PMC text mining. Sharing a sentence is not in itself a finding about the gene and the disease. The quoted sentences say what the papers report.
lung carcinoma (21 papers, 2019 to 2026). "HHLA2 expression in lung cancer is associated significantly with tumor characteristics and clinicopathological features." (PMID 38786018, 2024). "The function of HHLA2 was implicated in lung cancer in vitro following knockdown studies in lung cancer cell lines which resulted in decreased cancer cell proliferation." (PMID 36672492, 2023). "Expression of HHLA2 was lower in thyroid cancer and lung cancer samples compared with other respiratory-associated samples, and higher in UIP versus non-UIP ILD samples." (PMID 36675685, 2022). "This study reports that recently discovered, HHLA2 is over expressed in lung cancer associating with higher stage." (PMID 34181347, 2021). "In conclusions, This study suggests that recently discovered, HHLA2 is over expressed in lung cancer associating with higher stage." (PMID 34181347, 2021). "Additionally, HHLA2 expression was found to be elevated in lung cancer with EGFR mutation—one of the most common mutations in lung cancer." (PMID 38786018, 2024). "Notably, the correlation analysis from TCGA data pinpointed a significant positive association between LINC00665 and HHLA2, emphasizing their potential cooperative role in lung cancer progression." (PMID 38951802, 2024). "Further studies demonstrated that higher expression level of HHLA2 in human lung cancer tissues significantly associated with EGFR mutation, higher intensities of TILs and PD-L1 status, suggesting an effective immunotherapy strategy for PD-L1-negative patients." (PMID 31015801, 2019). "Emerging evidence identifies human endogenous retrovirus-H long terminal repeat-associating protein 2 (HHLA2), a novel B7 family member, as a genotype-associated immune checkpoint enriched in EGFR-mutant lung cancer." (PMID 42266686, 2026). "HHLA2, a recently identified member of the B7 family of immune checkpoints, has been shown to be highly expressed in lung cancer and colorectal carcinoma." (PMID 40746552, 2025). "HHLA2 is upregulated in lung cancer cells, and its genetic deletion inhibits NSCLC growth and polarization of tumor-associated macrophages (TAM) towards M2 phenotype." (PMID 38951802, 2024). "More reports concerning the potential therapeutic role of HHLA2 in lung cancer are needed to establish its role and clinical significance." (PMID 38786018, 2024). "Western blot analysis showed that TCF7 and HHLA2 were significantly upregulated in different lung cancer cell lines (all P < 0.05)." (PMID 38951802, 2024). "Further analysis revealed that LINC00665 recruits transcription factor TCF7 to upregulate HHLA2 expression in lung cancer cells, thereby facilitating lung cancer development and immune escape." (PMID 38951802, 2024). "LINC00665, through recruitment of TCF7 and upregulation of HHLA2, inhibits NK cell cytotoxicity, promoting the development and immune evasion of lung cancer." (PMID 38951802, 2024). "The results showed that, compared to adjacent tissues, the expression of TCF7 and HHLA2 mRNA in tumor tissues of lung cancer patients was significantly elevated (all P < 0.001)." (PMID 38951802, 2024). "We performed cell transfection to simultaneously knock down LINC00665 and overexpress HHLA2 in lung cancer cells (both P < 0.05) and examined their impact on the malignant behavior of lung cancer cells." (PMID 38951802, 2024). "In conclusion, our study unravels a novel regulatory network involving LINC00665, TCF7, HHLA2, and immune escape in lung cancer." (PMID 38951802, 2024). "In another study, 74.2% of 62 lung carcinoma samples expressed HHLA2, and HHLA2 expression correlated with metastases." (PMID 38786018, 2024). "Western blot results demonstrated that knocking down LINC00665 or TCF7 (all P < 0.001) significantly decreased the expression of HHLA2 in lung cancer cells (all P < 0.05)." (PMID 38951802, 2024). "Earlier, we confirmed that LINC00665 can upregulate the expression of HHLA2 in lung cancer cells by recruiting the transcription factor TCF7." (PMID 38951802, 2024).
lung carcinoma (continued). "In this regard, HHLA2 (along with other B7 family members) has been proposed as a potential immunotherapy target in lung cancers." (PMID 36675685, 2022). "Previous studies have illustrated that HHLA2 is mainly expressed in PD-L1-negative lung cancer compared with that in PD-L1-positive lung cancer." (PMID 33962626, 2021). "In the current study, we examined immunohistochemical HHLA2 expression in lung carcinoma specimens and its correlation to clinicopathological features." (PMID 34181347, 2021). "The wide expression of HHLA2 in lung cancer implicates the therapeutic potential of targeting those immune markers also in lung cancer." (PMID 34181347, 2021). "Further research is required to determine the biological significance and detect mechanisms of high HHLA2 expression in lung cancer and clarify its contributions in tumor immune escape." (PMID 34181347, 2021). "It was reported that HHLA2 promoted the progression of several human tumors, such as lung cancer, breast cancer, and oral cancer." (PMID 34152094, 2021). "HHLA2 expression was assessed in different pathological types of lung Cancer, and it was correlated with other clinicopathologic parameters and patient prognosis." (PMID 34181347, 2021). "Based on this, we hypothesized that LINC00665 could promote the transcription of HHLA2 in lung cancer cells by recruiting the transcription factor TCF7, thereby participating in the regulation of NK cell cytotoxicity." (PMID 38951802, 2024). "We further investigated whether LINC00665 could regulate the malignant behavior of lung cancer cells by upregulating HHLA2." (PMID 38951802, 2024). "To validate this hypothesis, we first used qRT-PCR to detect the expression of TCF7 and HHLA2 in tumor tissues of lung cancer patients and metastatic lung cancer patients." (PMID 38951802, 2024). "Studies have confirmed that HHLA2 is highly expressed in most malignant tumor tissues, including breast cancer, lung cancer, thyroid cancer, melanoma and pancreas adenocarcinoma, ovarian cancer, liver cancer, bladder cancer, colon cancer, prostate cancer, kidney cancer, and esophageal cancer." (PMID 35287670, 2022). "Few studies were done on the prognostic value of HHLA2 in lung cancer." (PMID 34181347, 2021). "The current study assesses HHLA2 immunohistochemical expression lung Cancer." (PMID 34181347, 2021). "This indicates that HHLA2 could be an appropriate alternative for targeting PD-L1 in lung cancer." (PMID 38786018, 2024). "EGFR, MSLN, MUC1, CEA, PD-L1, ROR1, HHLA2 (also referred to as B7H7), HER2, and various other target antigens are being studied for CAR-T therapy in lung cancer." (PMID 38622705, 2024). "The results showed that overexpression of HHLA2 partially reversed the inhibitory effects of LINC00665 knockdown on the proliferation, migration, invasion, and promotion of apoptosis in lung cancer cells (all P < 0.05)." (PMID 38951802, 2024). "LINC00665, TCF7 mRNA, and HHLA2 mRNA expression levels were significantly higher in lung cancer tissues than adjacent tissues, with non-metastatic lung cancer showing higher expression than metastatic lung cancer." (PMID 38951802, 2024). "However, there is currently no research reporting whether LINC00665 can promote the expression of HHLA2 in lung cancer cells and inhibit NK cell cytotoxicity by targeting binding TCF7, leading to immune escape and the development of lung cancer." (PMID 38951802, 2024). "Based on these analyses, we hypothesize that LINC00665 may promote the transcription of HHLA2 in lung cancer cells by recruiting transcription factor TCF7, thereby inhibiting NK cell cytotoxicity and promoting immune escape and the development of lung cancer." (PMID 38951802, 2024). "Human endogenous retrovirus‐H Long repeat‐associating 2 (HHLA2, also known as B7H5/B7H7/B7y), as a new member of B7 family, was reported to be overexpressed in multiple human cancers, such as lung cancer, triple‐negative breast cancer, osteosarcoma, and renal cell cancer." (PMID 34152094, 2021).
lung carcinoma (continued). "Similarly HHLA2 expression was not correlated to lymph node status in lung cancer." (PMID 34181347, 2021).
clear cell renal cell carcinoma (17 papers, 2019 to 2025). "In breast cancer, clear cell renal cell carcinoma, colorectal cancer, and osteosarcoma, high HHLA2 expression is associated with invasive tumour behaviour and worse clinical outcomes." (PMID 33962626, 2021). "HHLA2 knockdown in clear cell renal cell carcinoma (ccRCC) is reported to significantly associated with reduced vimentin and N-cadherin expressions and increased E-cadherin expression, which is indicative of a positive correlation between HHLA2 with cancer stemness profile of cancer." (PMID 38144305, 2023). "Upregulation of HHLA2 was associated with poor clinical features and outcomes in breast cancer, clear cell renal cell carcinoma, colorectal cancer, and osteosarcoma, whereas downregulation of HHLA2 might be beneficial for gastric cancer and epithelial ovarian cancer." (PMID 34660778, 2021). "Our present findings suggested that HHLA2 expression in human clear cell renal cell carcinoma is significantly associated with patient’s prognosis and promotes cancer progression, and could serve as important prognostic predictor and therapeutic target for this malignancy." (PMID 31015801, 2019). "Several studies aimed to investigate HHLA2 expression in clear cell renal cell carcinoma (ccRCC), demonstrating its significant upregulation in cancerous tissue in comparison with normal tissues." (PMID 38786018, 2024). "In conclusion, up-regulated HHLA2 level indicates severer pathology and worse prognosis for different cancers, such as clear cell renal cell carcinoma (ccRCC), intrahepatic cholangiocarcinoma (ICC) and osteosarcoma." (PMID 36003385, 2022). "This study aimed to reveal the expression landscape of HHLA2 in various solid tumors, and to evaluate its prognostic value in kidney clear cell carcinoma (KIRC)." (PMID 32509772, 2020). "Furthermore, elevated HHLA2 expression in ESCC, clear cell renal cell carcinoma, and pancreatic dual adenocarcinoma has been associated with better prognosis." (PMID 40746552, 2025). "Interestingly, a unique prognostic role of HHLA2 was observed in renal clear cell carcinoma compared with other tumor types." (PMID 31379814, 2019). "Combing with the result of expression profiling analysis, HHLA2 abounds in human normal and malignant tissue, however only differentially expressed in some tumor types (KIRC, COAD etc.), the subsequent studies will focus on the unique role of HHLA2 in renal clear cell carcinoma." (PMID 31379814, 2019). "However, in the result of pan-cancer survival analysis, we observed a unique and evident prognostic role of HHLA2 in kidney clear cell carcinoma comparing to other human cancers." (PMID 31379814, 2019). "Moreover, HHLA2 expression has been associated with the expression of ferroptosis-related gene ChaC Glutathione Specific Gamma-Glutamylcyclotransferase 1 (CHAC1), another prognostic factor in clear cell renal cell carcinoma." (PMID 38786018, 2024). "In addition, our study showed that tumoral HHLA2/PD-L1 coexpression was observed in most chordoma cases and could also independently predict prognosis, which was in line with the findings in clear cell renal cell carcinoma." (PMID 35145510, 2021). "Also, immune checkpoint HHLA2 was observed to be up-regulated in clear cell renal cell carcinoma and HHLA2 overexpression leads to a remarkable shorter OS and poorer prognosis, implying it could be a potential prognostic biomarker." (PMID 31324732, 2019). "The positive rate of HHLA2 expression in ovarian cancer tissues in the current study was 17.2% (11/64), which was considered a low percentage compared with 61 ~ 66% in NSCLC, 47.6% in colorectal cancer, 50% in clear cell renal cell carcinoma, and 56% in triple-negative breast cancer." (PMID 33962626, 2021).
gastric cancer (17 papers, 2018 to 2025). A primary or metastatic malignant neoplasm involving the stomach. "While HHLA2’s oncogenic potential has been suggested in other cancers, such as lung and gastric cancer, the underlying mechanisms remained unclear." (PMID 40394703, 2025). "HHLA2 overexpression is also found in other carcinomas like intrahepatic cholangiocarcinoma, stomach cancer, and colorectal cancer and is associated with poor prognosis." (PMID 36618968, 2022). "Accordingly, HHLA2 expression was associated with less aggressive tumor behavior in patients with gastric cancer." (PMID 29774123, 2018). "In gastric cancer, lower levels of HHLA2 mRNA in the blood was reportedly associated with tumor aggressiveness, adverse prognosis, and lesser 5-year survival rates, whereas the overexpression of HHLA2 in cancer tissues was correlated with poor overall survival." (PMID 36598731, 2023). "Taken together, these data indicate that knockdown of HHLA2 expression can inhibit the viability of human gastric cancer cells." (PMID 38762741, 2024). "HHLA2 in gastric cancer tissues was expressed mainly in the membrane or cytoplasm of both healthy epithelial cells and tumor cells." (PMID 38786018, 2024). "The authors examined 408 gastric cancer and 211 normal tissue specimens and found HHLA2 to be significantly upregulated in the tumor tissues." (PMID 38786018, 2024). "The 5-year survival rate of patients with gastric cancer was significantly higher in patients with HHLA2 highly expressed." (PMID 35565241, 2022). "By contrast, a high HHLA2 level predicts better survival in gastric cancer and pancreatic ductal adenocarcinoma." (PMID 33962626, 2021). "In contrast, in gastric cancer, patients with high HHLA2 mRNA levels in peripheral blood have a higher 5-year survival rate than those with low HHLA2 levels, and HHLA2 mRNA levels have a significant negative association with invasive tumour behaviours." (PMID 33962626, 2021). "Although human endogenous retrovirus-H long terminal repeat-associating protein 2 (HHLA2) is a novel molecule of the B7/CD28 family, the clinical impact of its expression remains uncertain in gastric cancer." (PMID 29774123, 2018). "In conclusion, the findings of this study demonstrate that HHLA2 expression is related to tumor progression and prognosis in patients with gastric cancer." (PMID 29774123, 2018). "Blood specimens obtained from patients with gastric cancer had significantly lower copies of HHLA2 mRNA than those obtained from healthy volunteers (P < 0.0001)." (PMID 29774123, 2018). "In the current study, we investigated HHLA2 protein expression in resected tumor tissues obtained from patients with gastric cancer, including normal epithelium of the stomach, using immunohistochemistry." (PMID 29774123, 2018). "We evaluated HHLA2 mRNA levels using the qRT-PCR assay in four gastric cancer cell lines, 111 blood specimens obtained from patients with gastric cancer, and 20 peripheral blood mononuclear cell (PBMC) specimens obtained from healthy volunteers." (PMID 29774123, 2018). "HHLA2 protein expression was assessed by immunohistochemistry of 73 tumor tissues resected from patients with gastric cancer." (PMID 29774123, 2018). "In this study, we focused on the clinical significance of HHLA2 expression in blood specimens obtained from patients with gastric cancer." (PMID 29774123, 2018). "In the blood specimens obtained from patients with gastric cancer, the relative number of HHLA2 mRNA copies ranged from 0.0214 to 1.30." (PMID 29774123, 2018). "The purpose of the current study was to examine the expression of HHLA2 in blood specimens and to compare the status of its expression between blood and primary tumor specimens obtained from patients with gastric cancer." (PMID 29774123, 2018). "The prognostic role of HHLA2 in gastric cancer remains to be elucidated." (PMID 38786018, 2024).